NPM1 (nucleophosmin 1)
Diseases named in the same sentence as NPM1 in open-access papers (continued):
Sharing a sentence is not in itself a finding about the gene and the disease.
leukemia (continued). "Considering that aberrant cytoplasmic localization of PML was mediated by NPM1-mA in NPM1-mutated leukemia cells 27, we next investigated the effects of NPM1-mA on VCAN-V1 expression." (PMID 31777586, 2019). "As INPP4B protein expression seems largely correlated with its mRNA expression in NPM1-mutated leukemia cells, it is likely that INPP4B is elevated by transcriptional mechanisms." (PMID 29343273, 2018). "Several BET inhibitors are in development and have been shown to have activity across various subtypes of AML in mouse models including MLL-fusion leukemias, as well as leukemias bearing mutations in NPM1, Flt3-ITD and DNMT3A." (PMID 29545928, 2018). "Considering the activation of SGK3 in NPM1-mutated leukemia cells, we assessed the role of SGK3 in INPP4B-mediated cell proliferation." (PMID 29343273, 2018). "We evaluated the potential molecular mechanism underlying INPP4B upregulation in leukemia cells with NPM1-mA." (PMID 29343273, 2018). "To explore the potential mechanisms by which INPP4B contributes to cell proliferation in NPM1-mutated leukemia, we performed siRNA-mediated knockdown of INPP4B in OCI-AML3 cells, and the phosphorylation (activation) of SGK3 and AKT was then monitored." (PMID 29343273, 2018). "Previous reports and the present study suggest that INPP4B provides a survival advantage through the activation of SGK3 in NPM1-mutated leukemia cells." (PMID 29343273, 2018). "This suggests that upregulation of INPP4B/SGK3 was at least partially caused by NPM1-mA expression in leukemia cells." (PMID 29343273, 2018). "In summary, for the first time to our knowledge, our data suggest that overexpression of INPP4B promotes NPM1-mutated leukemia cell proliferation through SGK3 activation." (PMID 29343273, 2018). "Described here, increased levels of the protein-coding NPM1 transcripts in leukemia support the association of NPM1 gene expression with leukemogenesis." (PMID 30126426, 2018). "Where available, however (currently only for “favorable risk” subtypes, e.g., APL, core binding factor leukemia, and NPM1-mutated AML), molecular methods are preferred because of their high reproducibility and inter-center standardization." (PMID 28925935, 2017). "Mutations in other common leukemia-related genes such as nucleophosmin 1 (NPM1), CCAAT/enhancer-binding protein alpha (CEBPA), and Wilms tumor 1 (WT1) have been found to occur as both preleukemic and late events." (PMID 29164062, 2017). "Inhibition by DOT1L and the menin-MLL pathways can release the block on NPM1-mutated leukemia and result in differentiation." (PMID 28420416, 2017). "Disruption of the NoLS and appearance of a new NES account for the aberrant cytoplasmic localization of mutated NPM1, which is the hallmark of this kind of leukemia (hence mutated NPM1 is also termed NPM1c+, from cytoplasmic positive)." (PMID 27058426, 2016). "A wealth of different data suggests that NPM1 mutations act as a founder genetic lesion in this kind of leukemia and therefore AML with NPM1 mutation has been included as a new provisional entity in the WHO 2008 classification of myeloid neoplasms." (PMID 27058426, 2016). "Considering the high levels of miR-10b in NPM1-mutated leukemia cells, we examined the impact of miR-10b on NPM1-mA mediated differentiation inhibition." (PMID 27669739, 2016). "Some of the PPP3CA interactor proteins implicated in leukemia pathobiology such as BCL11b, NPM1, GSK3β and Rb were further validated in Jurkat T-ALL cells expressing constitutively active PPP3CA*." (PMID 27304189, 2016). "Since leukemia cells bearing NPM1 mutations frequently show myelomonocytic or monocytic features with dysplasia of two or more cell lineages, we selected the THP-1 cell line derived from human monocytic leukemia as a cellular model for experiments." (PMID 27669739, 2016).
leukemia (continued). "Similar to SET, NPM1 is a nuclear protein that has been implicated in the onset of leukemia and that can shuttle from the nucleus to the cytoplasm and vice versa." (PMID 23874639, 2013). "Importantly, MI‐3454 produced lasting responses in patient‐derived xenografts of both KMT2A‐rearranged and NPM1‐mutated leukemia." (PMID 39887730, 2026). "Our analysis of transcriptional heterogeneity underscores the importance of targeted therapies that exploit biological vulnerabilities, such as the use of menin inhibitors in KMT2Ar or NPM1‐mutated leukemias, or combinatorial immunotherapeutic approaches that span the diverse pAML landscape." (PMID 41178390, 2025). "Menin functions as an obligate chromatin scaffold, anchoring KMT2A (MLL) fusion complexes to HOX loci in concert with LEDGF and the SEC/DOT1L machinery, sustaining a HOX/MEIS-high transcriptional state that defines KMT2A-rearranged leukemia and ∼30% of NPM1-mutated AML." (PMID 41347170, 2025). "Indeed, NPM1 is one of the most commonly mutated genes, occurring in approximately 30% of adult leukemia cases with normal karyotype." (PMID 38612443, 2024). "In summary, our study provides a comprehensive overview of concomitant mutations within our NPM1-mutated leukemia cohort, highlighting significant differences between patient fingerprinting at the genetic/transcriptional level and “standard” diagnostic assessment." (PMID 38612443, 2024). "In addition, it is worth mentioning that mutated FLT3 (ITD) and mutated NPM1 are also leukemia-specific target antigens in AML, which are associated with CD8+ T-cell responses." (PMID 39582863, 2024). "Furthermore, mutated FLT3 (ITD) and NPM1 are leukemia-specific target antigens in AML, associated with CD8+ T-cell responses." (PMID 39582863, 2024). "While NPM1 is implicated in retinoic acid–induced leukemia cell differentiation, it is uncertain whether mutated NPM1 retains this functionality." (PMID 39432585, 2024). "NPM1 mutations result in a stronger nuclear export signal than the nuclear localization signal, leading to abnormal cytoplasmic localization of the mutated NPM1 protein, which is considered to play a crucial role in leukemia occurrence." (PMID 38671491, 2024). "Therefore, a deeper exploration of other biological functions of TP53INP2 contributes to revealing its distinct role in NPM1-mutated leukemia." (PMID 36675134, 2023). "Indeed, RNA-seq data from another study also indicated the upregulation of TP53INP2 in NPM1-mutated leukemia cells." (PMID 36675134, 2023). "We found that mutated-NPM1-specific CTLs, displaying specific cytokine production and high-level cytotoxicity against patients’ leukemia blasts, and limited inhibitory activity in clonogenic assays, could be obtained from both patients and donors." (PMID 37345068, 2023). "Besides its oncogenic activity in KMT2Ar and mutated NPM1 leukemia, menin can directly interact with chromatin histones too." (PMID 37816719, 2023). "Next, we attempted to explore the biological function of TP53INP2 in NPM1-mutated leukemia cells." (PMID 36675134, 2023). "However, a study in an NPM1-mutated transgenic mice model indicated that NPM1 mutation alone is insufficient to initiate leukemia, suggesting the need for exploring other underlying oncogenic events in NPM1-mutated AML." (PMID 36675134, 2023). "The aim of our study was to assess the feasibility of obtaining a cell therapy medicinal product specific for the mutated NPM1 protein from patients or healthy donors that could be employed to control leukemia and prevent hematologic relapse." (PMID 37345068, 2023). "Furthermore, the ribosome biogenesis factor NPM1 (B23) is mutated in about a third of all leukaemia cases." (PMID 37526268, 2023). "Our findings indicate that NPM1mut-CTLs, obtained from patients or healthy donors and endowed with leukemia-specific activity, may constitute a safe and effective option in the treatment of patients affected by refractory or relapsed NPM1-mutated AML." (PMID 37345068, 2023).
leukemia (continued). "Another leukemia specific target antigen employed for cellular therapies is mutated NPM1." (PMID 36555547, 2022). "DLI using T cells derived from healthy donors and specifically directed against the NPM1-mutated neoantigen with the aim to elicit graft-versus-leukemia may be a therapeutic option in patients experiencing molecular relapse following allogeneic HSCT." (PMID 36008542, 2022). "FLT3, CEPBA and NPM1 are commonly mutated genes in leukaemia." (PMID 36286062, 2022). "Furthermore, cellular therapies have been designed to enable alloreactive immunity by allogeneic NK cells or target leukemia antigens such as mutated NPM1." (PMID 36555547, 2022). "PROTAC promoted degradation of fused oncoproteins in MLL leukemia subtypes and its use could be extended to NPM1-mutated AML." (PMID 36008542, 2022). "Alternatively, neoantigen-specific donor lymphocyte infusion derived from healthy donors and targeting NPM1-mutated protein to selectively elicit graft-versus-leukemia effect may represent an attractive option in subjects experiencing post-HSCT relapse." (PMID 34502069, 2021). "Additionally, other HOX cluster lncRNAs, such as HOXA10-AS and HOXB-AS3, have been reported to be significantly overexpressed in NPM1-mutated leukemia cells." (PMID 34615546, 2021). "Of further interest, NSG mice injected intravenously with OCI-AML3 leukemic cells and receiving treatment with NPM1-mutated CAR-T cells showed a significant reduction in leukemia burden, resulting in prolonged survival compared to mice treated with untransduced T cells." (PMID 34502069, 2021). "Biologically, this report reinforces the concept of NPM1 as ‘born-to be-exported’ in NPM1-mutated AML, meaning that only those mutations that lead to exportin-1(XPO1)/NPM1 mutant interaction and the following dislocation of NPM1 in the cell cytoplasm are selected to develop leukemia." (PMID 34573408, 2021). "NPM1 is considered as one of the early cooperating mutations in leukemia leukemogenesis." (PMID 33836835, 2021). "Furthermore, FLT3-ITD leukemias with mutations in NPM1 or DNMT3A exhibit a different drug response mechanism to the FLT3 inhibitor quizartinib, where the cell differentiation effect predominates over the cytotoxic mechanism." (PMID 33592069, 2021). "Furthermore, these inhibitors display pronounced growth suppressive activity in MLL1-r or NPM1-mutated leukemia mouse models and a minimal effect in human leukemia cell lines without MLL translocations." (PMID 34698191, 2021). "Next, we explored the biological effects of high HOTAIRM1 expression in NPM1-mutated leukemia." (PMID 34615546, 2021). "NPM1 alterations were reported as definite leukemia-founder mutations and optimal MRD markers." (PMID 34153064, 2021). "Indeed, NPM1 mutation drives leukemia in mice when co-expressed with commonly co-occurring mutations." (PMID 34573408, 2021). "Multiple mechanisms through which mutations in NPM1 lead to leukemia have been described." (PMID 32545659, 2020). "In particular, the unique C-terminal sequences of mutated NPM1 in NPM1-mutant AML have been investigated as potential leukemia specific antigens that may elicit endogenous T cell responses and could also serve as targets for immunotherapy." (PMID 31781488, 2019). "In this latter instance, “neoantigen-specific DLI” to elicit graft-versus-leukemia could be an attractive option for NPM1-mutated AML patients, experiencing either morphologic or molecular relapse after allogeneic HSCT." (PMID 30783516, 2019). "Leukemias with mutated NPM1 have been recognized as a specific subgroup of AML." (PMID 31234353, 2019). "We then proceeded to assess whether NPM1-mutated-specific cytotoxic T cells had the ability to recognize and kill leukemia blasts." (PMID 30783516, 2019). "Here we tested whether VCAN-V1 was involved in the regulation of NPM1-mutated leukemia cells invasion." (PMID 31777586, 2019).
leukemia (continued). "In addition, there was a unique association between NPM1 mutation status and the presence of leukemia cutis, the infiltration of skin with leukemia cells." (PMID 31777586, 2019). "Collectively, these findings support the hypothesis that INPP4B activates SGK3 signaling, to promote cell proliferation in NPM1-mutated leukemia." (PMID 29343273, 2018). "Thus, in addition to SGK3, the other potential mechanisms underlying oncogenic role of INPP4B in NPM1-mutated leukemia cells needs to be determined." (PMID 29343273, 2018). "Interestingly, it has also been suggested that ATRA and arsenic trioxide combination can selectively induce apoptosis and differentiation in NPM1-mutated cells, as well as promote leukemia regression in elderly patients unfit for induction chemotherapy." (PMID 29301553, 2018). "First of all, we wanted to check whether NPM1 gene is upregulated in leukemia similarly as in other human neoplasms and whether NPM1 expression depends on the mutation status of the gene." (PMID 30126426, 2018). "Next, we explored the biological effects of INPP4B overexpression in NPM1-mutated leukemia." (PMID 29343273, 2018). "The level of NPM1.2 transcript in NPM1-mutated leukemia was close to the level noted for HV." (PMID 30126426, 2018). "In addition, the molecular mechanism underlying INPP4B expression in NPM1-mutated leukemia cells was explored." (PMID 29343273, 2018). "Finally, we found that heterozygous expression of a leukemia-associated NPM1 mutant significantly decreases the RNA binding level." (PMID 29507312, 2018). "Indeed, stem cell/progenitor cell surface marker CD34+ cells from NPM1-mutated AML patients are able to recapitulate leukemia in immunodeficient mice." (PMID 28197208, 2017). "However, little is known about the specific impact of NPM1 mutations and miRNA expression on leukemia cell differentiation." (PMID 27669739, 2016). "Our clinical results are supported by recent in vitro data in cell lines and primary AML blasts showing the ability of ATRA to induce a significant amount of apoptosis in some (3 out of 11) primary leukemia samples from patients with NPM1 mutation which was potentiated by combination with ATO." (PMID 27696203, 2016). "In light of these findings, we hypothesized that NPM1 mutations might inhibit myeloid differentiation of leukemia cells." (PMID 27669739, 2016). "Interestingly, several proteins implicated in leukemia pathobiology emerged amongst the novel PPP3CA interactors such as NPM1, BCL11b, GSK3β and KDM1 (also known as LSD1)." (PMID 27304189, 2016). "The NPM1 mutation is likely to occur very early during the pathogenesis of leukemia." (PMID 25386341, 2014). "Abnormal expression of NPM may lead to the oncogenesis of some types of leukemia as NPM1 gene is a partner in several tumor associated chromosomal translocations." (PMID 20979630, 2010). "Moreover, recognizing the heightened susceptibility of KMT2A-rearranged (KMT2Ar) leukemias to apoptosis induction through BCL2 inhibition, recent observations have shown synergistic activity in models of KMT2Ar or NPM1-mutated (NPM1mt) leukemia with dual Bcl-2 and menin inhibition." (PMID 38673842, 2024). "However, additional, complementary strategies, such as mutated-NPM1 specific cellular therapy, could represent a tool to prevent tumor outgrowth and escape, and further increase the probability of leukemia control." (PMID 37345068, 2023). "Therefore, further studies are needed to investigate whether TP53INP2 regulates other autophagy-related components to engage in the autophagy process in NPM1-mutated leukemia." (PMID 36675134, 2023). "Our finding that the primitive gene expression signature of NPM1-mutated AML cases was enriched for stem/progenitor genes supports the idea that the significant immunophenotypic clusters in primitive cases may be enriched for leukemia stem cells." (PMID 33594052, 2021).
leukemia (continued). "Additionally, no aminoacidic sequences from normal human tissues present in databanks match that of the 11 residues from the C-terminal NPM1-mutated protein, suggesting that this aminoacidic sequence may clearly serve as a leukemia-specific antigen." (PMID 34502069, 2021). "Additionally, the enrichment of FLT3-like leukemias in IDH1 mutations (which are correlated with NPM1 mutation) could set the basis for the development of new clinical trials testing the combination of different check-point inhibitors in AML." (PMID 33592069, 2021). "NPM1 mutations are always heterozygous, which may indicate that the interaction of the wild type and mutant proteins is required for the survival of leukemia cells." (PMID 34944812, 2021). "Furthermore, since NPM1-mutated leukemia cells are associated with increased CD33 expression, CD33 antibodies like gemtuzumab ozogamicin (GO) could be a targeted therapy for those NPM1-mutated patients with high CD33 expression." (PMID 29301553, 2018). "In vivo, this combination reduced leukemia burden and improved survival, suggesting a promising therapeutic strategy for AML with NPM1 or KMT2A‐r mutations and FLT3 mutations." (PMID 39887730, 2026). "Menin inhibitors are a novel class of targeted therapies under active clinical investigation for their potential in treating acute leukemias, particularly KMT2A‐rearranged and NPM1‐mutant leukemias." (PMID 40181550, 2026). "In preclinical models, various Menin inhibitors have now shown remarkable effectiveness in treating KMT2A‐rearranged, NPM1‐mutated, and NUP98‐rearranged leukemia." (PMID 39887730, 2026). "The drug combination also showed greater inhibition of cell proliferation and increased apoptosis in NPM1 mutated and KMT2A‐rearranged leukemia models with FLT3 mutations." (PMID 39887730, 2026). "Another class of clinically available molecules that show synergy with Menin inhibitors in KMT2A‐rearranged and NPM1 mutant leukemia are immunomodulatory drugs (IMIDs), like Lenalidomide, Pomalidomide or Mezigdomide." (PMID 39887730, 2026). "Since NPM1 mislocalization is a driver of leukemia, we first examined the subcellular profile of NPM1 across a panel of 9 human myeloid and lymphoid leukemia cell lines, one of which harbors the NPM1c mutation (OCI-AML3)." (PMID 40269321, 2025). "Outside of leukemia, autoantibodies in the sera from prostate cancer patients were shown to react with NPM1, while healthy controls did not23, indicating potential aberrant cell-surface localization leading to immune recognition." (PMID 40269321, 2025). "NPM1-mutated AML has a favorable prognosis and is defined as a distinct leukemia entity in the World Health Organization classification." (PMID 40557158, 2025). "It is therefore important to explore the molecular links between oligomerisation and NPM1-driven leukaemia." (PMID 40260502, 2025). "EPZ-5676 downregulates HOXA9/PBX3 expression and induces apoptosis in NPM1-mutated leukemia cells, establishing its therapeutic potential for MLL-r leukemias." (PMID 41199817, 2025). "JNJ-75,276,617 is an effective, selective inhibitor targeting the Menin-KMT2A interaction, demonstrating efficacy in leukemia cell lines and patient samples with KMT2A-rs or NPM1 mutations." (PMID 40361241, 2025). "Despite our increasing knowledge of the pathogenesis and treatment options of NPM1-mutated AML, there are many unanswered questions concerning this subtype of leukemia." (PMID 40647396, 2025). "As a result, 88% of the study population had KMT2A-r or NPM1-m leukemia at the time of the reported data analysis." (PMID 39179671, 2024). "The trial was later amended to limit enrollment to patients with KMT2A-r or NPM1-m leukemia because preclinical data demonstrated the efficacy of targeting the KMT2A-menin interaction." (PMID 39179671, 2024). "The mouse models of NPM1-fusion leukemia established in this study will be useful tools for understanding the pathogenesis of AML with NPM1 abnormalities." (PMID 39443736, 2024).